KHSRP (KH-type splicing regulatory protein)
Description:
Binds to the dendritic targeting element and may play a role in mRNA trafficking (By similarity). Part of a ternary complex that binds to the downstream control sequence (DCS) of the pre-mRNA. Mediates exon inclusion in transcripts that are subject to tissue-specific alternative splicing. May interact with single-stranded DNA from the far-upstream element (FUSE). May activate gene expression. Also involved in degradation of inherently unstable mRNAs that contain AU-rich elements (AREs) in their 3'-UTR, possibly by recruiting degradation machinery to ARE-containing mRNAs.
Synonyms: KSRP; FUBP2; FBP2; p75
Tractability: PROTAC: UniProt records ubiquitination sites on it; ubiquitination databases record sites on it; its protein half-life has been measured.
Target class: Transcription factor
Gene: Protein-coding gene on chromosome 19 (6,413,102 to 6,424,811, reverse strand). Ensembl gene ENSG00000088247.
Subcellular location: Nucleus; Cytoplasm
Subcellular location (Human Protein Atlas): Nucleoplasm
Pathways (Reactome):
Cellular responses to stimuli: ATF4 activates genes in response to endoplasmic reticulum stress
Metabolism of RNA: KSRP (KHSRP) binds and destabilizes mRNA
Gene Ontology:
Molecular function: mRNA 3'-UTR AU-rich region binding; protein binding; protein folding chaperone; RNA binding; mRNA 3'-UTR binding; mRNA binding; nucleic acid binding
Biological process: 3'-UTR-mediated mRNA destabilization; cellular response to cytokine stimulus; miRNA metabolic process; negative regulation of low-density lipoprotein particle clearance; negative regulation of nitric oxide biosynthetic process; positive regulation of mRNA catabolic process; regulation of mRNA stability; mRNA processing; RNA splicing; RNA splicing, via transesterification reactions; protein folding; regulation of DNA-templated transcription
Cellular component: membrane; nucleoplasm; cytosol; exosome (RNase complex); cytoplasm; nucleus
Genetic constraint (gnomAD): Loss-of-function variants: 13 observed, 78.69 expected, observed/expected ratio (o/e) 0.17, 90% interval 0.11 to 0.26. The synonymous counts are far from expectation, so gnomAD's model fits this gene poorly and the ratio says little. Missense variants: 624 observed, 865.43 expected, observed/expected ratio (o/e) 0.72, 90% interval 0.67 to 0.77. Synonymous variants: 439 observed, 347.39 expected, observed/expected ratio (o/e) 1.26, 90% interval 1.17 to 1.37.
Homologues: Orthologues: dog KHSRP (99% identical), pig KHSRP (99% identical), mouse Khsrp (98% identical), rat Khsrp (97% identical), chimpanzee KHSRP (96% identical), macaque KHSRP (95% identical), guinea pig KHSRP (87% identical), tropical clawed frog khsrp (69% identical), zebrafish khsrp (65% identical), Caenorhabditis elegans fubl-3 (26% identical), Caenorhabditis elegans fubl-4 (24% identical), Drosophila melanogaster mub (13% identical), and 5 more. Paralogues in human: FUBP1 (57% identical), FUBP3 (41% identical), IGF2BP2 (16% identical), IGF2BP3 (15% identical), NOVA1 (14% identical), PCBP4 (14% identical), IGF2BP1 (14% identical), NOVA2 (14% identical), PCBP2 (14% identical), PCBP3 (13% identical), PCBP1 (13% identical), HNRNPK (12% identical).
Diseases named in the same sentence as KHSRP in open-access papers:
KHSRP is named in the same sentence as 74 diseases in open-access papers, as found by Europe PMC text mining. Sharing a sentence is not in itself a finding about the gene and the disease. The quoted sentences say what the papers report.
lung carcinoma (11 papers, 2017 to 2025). "Although KHSRP has been implicated in lung cancer progression, its molecular mechanisms and impacts on chemotherapy sensitivity remain elusive." (PMID 41194272, 2025). "Currently, the identities of KHSRP-associated signaling molecules that are responsible for mediating human lung cancer cell metastasis are unclear." (PMID 31775888, 2019). "Some studies have demonstrated that KHSRP silencing reduced cell proliferation, migration, and invasion in NSCLC, and lung cancer patients with high KHSRP expression had poorer survival." (PMID 41194272, 2025). "Knockdown of KHSRP significantly reduced lung cancer cell proliferation, migration, and invasion in vitro and in vivo, and survival analysis showed that patients with high KHSRP expression levels had poor prognoses." (PMID 33229623, 2020). "Kaplan-Meier survival analysis showed that higher expression levels of both KHSRP and HNRNPC were strongly associated with a shorter survival time for lung cancer patients." (PMID 31775888, 2019). "In NSCLC cell lines, knockdown of KHSRP significantly reduced lung cancer cell proliferation, migration, and invasion in vitro and in vivo, whereas overexpression of KHSRP did the opposite." (PMID 31775888, 2019). "However, other studies have shown that silencing KHSRP reduces cell proliferation, reverses anchorage-independent growth, and decreases migration and invasion, indicating a potential oncogenic role for KHSRP in lung cancer." (PMID 39866240, 2025). "Taken together, these findings indicate that KHSRP plays a critical role in lung cancer development and metastasis and might be a potential prognostic biomarker for this disease." (PMID 31775888, 2019). "We found that interference with KHSRP could inhibit the migration and invasion of lung cancer cells in vitro and inhibit the growth and metastasis of lung cancer cells in vivo." (PMID 31775888, 2019). "Overexpression of KHSRP activated IFN-αJAK-STAT1 signaling pathway and induced lung cancer cell invasion and metastasis." (PMID 34722250, 2021). "In this study, we demonstrated that KHSRP colocalized and coimmunoprecipitated with HNRNPC in lung cancer cells, suggesting that KHSRP can specifically interact with HNRNPC to form a complex in the nuclei of NSCLC cells." (PMID 31775888, 2019). "To investigate the functional roles of KHSRP in NSCLC cells, we first assessed the migration and invasion abilities of the four human lung cancer cell lines." (PMID 31775888, 2019). "KHSRP and HNRNPC may induce human lung cancer cell invasion and metastasis by activating the IFN-α-JAK-STAT1 signaling pathway." (PMID 31775888, 2019). "Meanwhile, KHSRP and HNRNPC can interact with each other and activate the IFN-α-JAK-p-STAT1 signaling pathway, which ultimately increases the invasion and metastasis of lung cancer cells." (PMID 31775888, 2019). "Regarding the function and role of KHSRP in lung cancer, the research results of different scholars have not been consistent." (PMID 31775888, 2019). "The results indicated that KHSRP could interact with HNRNPC and HNRNPC may promote the metastasis of lung cancer through IFN-α-JAK-p-STAT1 signaling pathway." (PMID 31775888, 2019). "Higher expression of KHSRP was observed in lung cancer tissues compared to that in adjacent noncancerous tissues." (PMID 31775888, 2019). "Importantly, KHSRP protein expression was positively correlated with that of HNRNPC, suggesting a potential KHSRP-HNRNPC pathway in lung cancer tissues (R = 0.481, P < 0.01)." (PMID 31775888, 2019). "To date, however, the molecular mechanisms by which KHSRP promotes lung cancer cell migration and invasion have not been elucidated." (PMID 31775888, 2019). "KHSRP plays an important role in NSCLC metastasis and may serve as a potential prognostic marker and novel therapeutic target for lung cancer metastasis treatment." (PMID 31775888, 2019).
lung carcinoma (continued). "HNRNPC overexpression was observed in a variety of human cancers, including lung cancer HNRNPC, as a protein-coding gene, could also interact with KHSRP to activate the IFN-α-JAK-p-STAT1 signaling pathway and promoted NSCLC cell proliferation, migration, and invasion." (PMID 34179079, 2021). "Drastically higher expression levels of KHSRP and HNRNPC were observed in lung cancer tissues compared to those in adjacent noncancerous tissues." (PMID 31775888, 2019).
non-small cell lung carcinoma (9 papers, 2017 to 2025). A group of at least three distinct histological types of lung cancer, including non-small cell squamous cell carcinoma, adenocarcinoma, and large cell carcinoma. "For example, KHSRP inhibits motility in brain tumors and non-small cell lung cancer (NSCLC); furthermore, it is associated with a good prognosis." (PMID 39439895, 2024). "For example, KHSRP can promote carcinogenesis and metastasis in non-small cell lung cancer and is associated with advanced tumor stages and shorter survival rates." (PMID 33638945, 2021). "KHSRP inhibits the invasion and migration of non-small cell lung cancer through the miR-23a/EGR3 axis." (PMID 39439895, 2024). "KHSRP is significantly expressed in highly metastatic non-small-cell lung carcinoma cells, and its depletion decreases tumorigenic phenotypes, including growth and metastasis, both in vitro and in vivo." (PMID 32967226, 2020). "In the present study, we investigated the function and potential molecular mechanism of KHSRP in non-small cell lung cancer (NSCLC) metastasis and elucidated its clinical significance." (PMID 31775888, 2019). "KHSRP (KH-type splicing regulatory protein) could promote invasion and metastasis of non-small-cell lung cancer by interacting with HNRNPC." (PMID 35897085, 2022). "In non-small cell lung cancer (NSCLC), KHSRP promotes the maturation of miR-23a precursors." (PMID 32967226, 2020).
breast carcinoma (8 papers, 2020 to 2025). "In summary, we have made a systematical analysis for exploring the downstream targets of KHSRP and trying to associate them with the functions of KHSRP in breast cancer cells." (PMID 38926398, 2024). "We found KHSRP showed higher expression level and was associated with worse prognosis in breast cancer patients." (PMID 38926398, 2024). "The KH-type splicing regulatory protein (KHSRP) participates in the development of breast cancer, while the underlying mechanisms are largely unknown." (PMID 38926398, 2024). "Finally, we used Kaplan–Meier Plotter32 to decipher the association between KHSRP expression and the survival time of breast cancer patients." (PMID 38926398, 2024). "In this study, we speculate that KHSRP may regulate the expression and alternative splicing of a large number of tumor-associated genes based on the fact that KHSRP was correlated with the development of breast cancer and poor prognosis of patients." (PMID 38926398, 2024). "Besides the higher expression and association with worse RFS of KHSRP in breast cancer patients, we found that KHSRP knockdown could inhibit cell proliferation, migration, and invasion, and promote cell apoptosis." (PMID 38926398, 2024). "In summary, our study comprehensively explored the downstream targets and their functions of KHSRP in breast cancer cells, highlighting the molecular mechanisms of KHSRP on the oncogenic features of breast cancer." (PMID 38926398, 2024). "In summary, the dysregulated genes by siKHSRP showed high consistency with the altered pro-oncogenic features of MDA-MB-231 cells, indicating that KHSRP affects breast cancer cell development by regulating the gene expression pattern." (PMID 38926398, 2024). "In this study, we identified the novel downstream targets and molecular functions of KHSRP in breast cancer." (PMID 38926398, 2024). "To obtain a further understanding of KHSRP in breast cancer patients, we utilized online tool UALCAN31 to explore its expression pattern in breast invasive carcinoma (BRCA) patients." (PMID 38926398, 2024). "Similar results were obtained for the protein level of KHSRP in breast cancer patients, indicating that KHSRP was consistently upregulated in breast cancer at both RNA and protein levels." (PMID 38926398, 2024). "In breast cancer, KHSRP was up-regulated and correlated with proliferation of tumor cells and poor prognosis of patients." (PMID 38926398, 2024). "RES promotes the epithelial-type alternative splicing of Cd44, Enah, and FGFR2 pre-mRNAs in breast cancer cells by upregulating KH-type splicing regulatory protein (KHSRP) and heterogeneous nuclear ribonucleoproteins A1 (hnRNPA1) expression." (PMID 33937049, 2021). "In summary, our study highlighted the potential regulatory mechanisms of KHSRP in breast cancer and identified substantial KHSRP downstream RNA molecules that could be used as potential therapeutic targets for breast cancer in future." (PMID 38926398, 2024). "In summary, our results demonstrated the potential oncogenic ability of KHSRP in breast cancer." (PMID 38926398, 2024). "Based on the results, we obtained a global view of KHSRP-regulated downstream targets, and understood how KHSRP promotes breast cancer progression; the identified molecular targets could be used as potential targets for breast cancer therapy in future." (PMID 38926398, 2024). "Moreover, likely obstruction of the post-transcriptional regulatory network in MCF7 breast cancer cells by knock-down of KHSRP significantly reduced cell proliferation upon CP treatment, emphasizing the role of RBPs in cancer biology and drug response." (PMID 31522610, 2020).
breast carcinoma (continued). "Therefore, we speculate that KHSRP may play a role in breast cancer by regulating both the expression and alternative splicing of DNA repair functional genes." (PMID 38926398, 2024). "We propose that KHSRP could modulate the progression of breast cancer by regulating the expression and AS patterns of these genes, suggesting novel molecular targets and therapeutic methods for breast cancer based on the KHSRP regulatory network in future." (PMID 38926398, 2024). "The drug disrupts the iron-homeostasis regulator KH-type Splicing Regulatory Protein (KHSRP), triggers an unconventional ferroptotic cascade, and overcomes paclitaxel resistance in breast cancer." (PMID 41008615, 2025). "However, the exact functions and molecular mechanisms of KHSRP in breast cancer are still unknown." (PMID 38926398, 2024). "Moreover, decreased CISD1 expression and elevated 4-HNE levels from SB-T-101141 induction were notably abolished by KHSRP depletion and DFOM in breast cancer cells." (PMID 40389408, 2025). "KH-type splicing regulatory protein (KHSRP) is a single-stranded multifunctional RNA-binding protein that is involved in posttranscriptional aspects of RNA metabolism and plays an important role in the development of breast cancer." (PMID 36052258, 2022).
glioblastoma (7 papers, 2015 to 2025). The most malignant astrocytic tumor (WHO grade IV). "KHSRP knockdown in glioblastoma multiforme (GBM) cells promotes migration and causes multifocal tumor in a mouse model." (PMID 29020972, 2017). "In addition, two independent studies have demonstrated that high KHSRP expression levels were associated with longer overall survival in glioblastoma multiforme." (PMID 29254151, 2017). "Indeed, analysis of the data curated by “The Cancer Genome Atlas Research Network” (TCGA) revealed that high KHSRP transcript levels are associated with increased overall survival in glioblastoma multiforme." (PMID 25993413, 2015). "In particular, SUMOylation can impact the subcellular distributions of proteins; for example, SUMOylated KHSRP is more likely to translocate from the nucleus to the cytoplasm than is unmodified KHSRP in glioblastoma multiform cells." (PMID 33761465, 2021).
colorectal cancer (5 papers, 2017 to 2025). A primary or metastatic malignant neoplasm that affects the colon or rectum. "A few of the Top 10 potential proteomic biomarkers revealed in our study have been previously identified as compounds associated with colorectal cancer’s response to RT, including CEACAM5, KHSRP, RALA, and TSPAN8." (PMID 38410100, 2024). "We also detected the SUMO1 modification of KHSRP in tumors and paracancerous tissues of gastric and colorectal cancer, respectively." (PMID 29020972, 2017). "In addition, the downregulation of KHSRP enhances the sensitivity to 5-fluorouracil in colorectal cancer." (PMID 33638945, 2021). "KHSRP was reported to be oncogenic in non-small lung cancer, colorectal cancer and PTC." (PMID 34722250, 2021). "Also, KHSRP functions as a pro-tumor factor in pancreatic cancer and colorectal cancer." (PMID 33638945, 2021).
esophageal squamous cell carcinoma (5 papers, 2017 to 2025). Esophageal squamous cell carcinoma (ESCC) is a type of esophageal carcinoma (EC) that can affect any part of the esophagus, but is usually located in the upper or middle third. "In the present study, we investigated the oncogenic functions of KHSRP and their underlying mechanisms in the pathogenesis of esophageal squamous cell carcinoma (ESCC)." (PMID 29254151, 2017). "Further, in 2017, study investigated the oncogenic functions of KH-type splicing regulatory protein (KHSRP) in esophageal squamous cell carcinoma (ESCC)." (PMID 39816132, 2025).